NOG (noggin)
Diseases named in the same sentence as NOG in open-access papers (continued):
Sharing a sentence is not in itself a finding about the gene and the disease.
ankylosis (3 papers, 2012 to 2024). Fixation and immobility of a joint. "Nevertheless, as a specific antagonist of BMP2, noggin still has broad application prospects for preventing ankylosis progression in AS." (PMID 31024000, 2019). "Human noggin (NOG) is a responsible gene for a wide range of clinical manifestations of stapes ankylosis with symphalangism." (PMID 22288654, 2012).
astrocytoma (3 papers, 2010 to 2026). "Analysis of the SHAP values for the remaining genes revealed that increased expression of ZDHHC18, HDAC1, and TUBB6 enhances the probability of predicting astrocytoma, while elevated expression of TERT, TRIM67, NOG, KCNIP2, and KCNJ11 increases the probability of predicting oligodendroglioma." (PMID 40867242, 2025).
brachydactyly type B2 (3 papers, 2017 to 2024). "Mutations in NOGGIN in humans leads to various phenotypes including brachydactyly type B2 (OMIM 611377) and various forms of synostosis/ankylosis/symphalangism (OMIM 186500, 184460, 185800, 186570)." (PMID 31637260, 2019). "Two closely related forms, Brachydactyly type B2 (BDB2) and BDB1 are caused by mutations in the BMP antagonist Noggin (NOG) and the atypical receptor tyrosine kinase ROR2 that acts as a receptor in the non-canonical Wnt pathway." (PMID 28523267, 2017). "Mutations in the BMP antagonist Noggin (NOG) and ROR2 cause Brachydactyly type B2 (BDB2)." (PMID 37307827, 2024).
glioma (3 papers, 2008 to 2026). A benign or malignant brain and spinal cord tumor that arises from glial cells (astrocytes, oligodendrocytes, ependymal cells). "This confirmed that gliomas with 1p19q codeletion overexpressed neuronal/normal brain genes (AKR1C3, C20orf42, CTTNBP2, L1CAM, GALNT13) as well as genes implicated in gliogenesis and neurogenesis (OLIG2, BMP2, NOG, DCX, ATOH8)." (PMID 18492260, 2008). "It was shown that Noggin does not affect the inhibition of E-cadherin expression by DAPT in LN18 glioma cells." (PMID 34104086, 2021). "We can exclude the possibility of autocrine BMP effects on DAPT-treated glioma cells because the BMP antagonist Noggin did not affect the repression of E-cadherin expression through Smad5 by DAPT treatment." (PMID 34104086, 2021).
osteoarthritis (3 papers, 2020 to 2025). A noninflammatory degenerative joint disease occurring chiefly in older persons, characterized by degeneration of the articular cartilage, hypertrophy of bone at the margins and changes in the synovial membrane. "In addition, we identify two independent genetic variants implicating noggin (NOG) as an osteoarthritis effector gene." (PMID 34450027, 2021).
pulmonary arterial hypertension (3 papers, 2016 to 2017). Pulmonary arterial hypertension (PAH) is a group of diseases characterized by mean pulmonary artery pressure >20 mmHg and elevated pulmonary arterial resistance leading to right heart failure. "BMP antagonists, such as gremlin and noggin, are potentially important mediators of vascular changes in hypoxic pulmonary hypertension, have been implicated plays an key role in the pathophysiology of pulmonary arterial hypertension." (PMID 28969002, 2017). "The feasibility of this approach has been demonstrated by studies using neutralizing antibodies against Noggin or Gremlin in the contexts of pulmonary arterial hypertension (PAH) and spinal cord injury." (PMID 27433166, 2016). "BMP signalling is negatively autoregulated by several genes including SMAD6, Noggin and Gremlin, and autoregulators are possible targets for enhancing BMP signalling in disorders such as fibrosis and pulmonary hypertension." (PMID 27324164, 2016).
Sepsis (3 papers, 2022 to 2025). Sepsis is defined as life-threatening organ dysfunction caused by a dysregulated host response to infection. "Three shared key genes (HCK, NOG, RNF125) were obtained, that have a good diagnostic value for both sepsis and ALL." (PMID 38123749, 2025). "Finally, ANKRD22, GPR84, GYG1, BLOC1S1, CARD11, NOG, and LRG1 were recognized as critical genes associated with sepsis molecular subtypes." (PMID 36035194, 2022). "In summary, this study is the first to analyze pediatric ALL and pediatric sepsis through bioinformatics, and three shared key genes (RNF125, NOG, and HCK) have been obtained." (PMID 38123749, 2025). "Previous bioinformatics analyses of pediatric ALL and pediatric sepsis cases have revealed three shared key genes (ring finger protein 125 (RNF125), noggin (NOG), and hemopoietic cell kinase (HCK))." (PMID 41007866, 2025).
acute renal failure (2 papers, 2015 to 2023). "Upregulation of Noggin has also been found as a critical factor in kidney regeneration in a rodent model of ischemia-induced acute renal failure." (PMID 37762531, 2023).
Cachexia (2 papers, 2023 to 2025). Severe weight loss, wasting of muscle, loss of appetite, and general debility related to a chronic disease. "Another discussed research was the cell-cell crosstalk in the cachexia through the signaling axis of muscle derived Noggin to inhibit the BMP signaling in neuronal cells at the neuromuscular junction, which further exacerbates the muscle wasting in cachexia." (PMID 41245273, 2025).
cleft palate (2 papers, 2012 to 2025). Cleft palate is a fissure type embryopathy that affects the soft and hard palate to varying degrees. "Experimental studies in Nog-knockout mice have demonstrated severe craniofacial malformations, including cleft palate and mandibular overgrowth, underscoring the critical role of noggin in craniofacial development." (PMID 40869901, 2025). "Noggin null mice show that without Noggin's repression of Bmp signaling, palate development does not proceed normally, with fusion between the palate and mandible ultimately leading to a cleft palate phenotype." (PMID 23316168, 2012).
colorectal cancer (2 papers, 2022 to 2023). A primary or metastatic malignant neoplasm that affects the colon or rectum. "In order to further investigate the effects of BMP‐9 and noggin on the normal gut mucosa as well as on colorectal cancer cells, we searched for a human in vitro model system." (PMID 34841646, 2022). "Significantly higher GREMLIN1, NOGGIN, and CXCL12 expression were detected in the Consensus Molecular Subtype 4 (CMS4) colorectal cancers, which are thought to arise from serrated polyps." (PMID 36326956, 2023).
fibrodysplasia ossificans progressiva (2 papers, 2011 to 2012). Fibrodysplasia ossificans progressiva (FOP) is a severely disabling heritable disorder of connective tissue characterized by congenital malformations of the great toes and progressive heterotopic ossification that forms qualitatively normal bone in characteristic extraskeletal sites. "Noggin mutations have also been reported in fibrodysplasia ossificans progressiva (FOP), which is a rare autosomal dominant disorder of skeletal malformations and progressive extraskeletal ossification caused mainly by mutations in the BMP type I receptor ACVR1." (PMID 21310029, 2011). "Involved in ossification of muscles and joints in fibrodysplasia ossificans progressiva (FOP) disease, through mutations in ACVR1 and noggin gene." (PMID 22934054, 2012).
hearing loss (2 papers, 2024 to 2025). "The phenotypic variability observed in individuals with NOG mutations, together with the role of noggin and BMP in development of mouse inner ear, suggests that NOG gene mutations contribute to the sensorineural component of hearing loss in humans." (PMID 41148756, 2025).
Intraventricular hemorrhage (2 papers, 2013 to 2016). Bleeding into the ventricles of the brain. "In animal models of demyelination and intraventricular hemorrhage, where levels of endogenous BMP signalling are increased, Noggin delivery increases oligodendrocyte numbers and decreases astrocyte numbers." (PMID 23650566, 2013). "Although the role of noggin as it relates to brain injury is not well described in the clinical literature, preclinical studies show that inhibition of BMP by noggin promotes neurological recovery from ischemic brain injury and recovery from intraventricular hemorrhage." (PMID 27468266, 2016).
lung carcinoma (2 papers, 2021 to 2023). "For example, low levels of Noggin have been associated with a more aggressive phenotype and increased invasion and metastasis of lung cancer cells." (PMID 38012621, 2023). "In addition, Noggin knockdown in control M0 cells promoted cell attachment and suppressed cell migration, suggesting that Noggin reduction during brain colonization causes inhibition of migration and invasion of metastatic lung cancer cells." (PMID 38012621, 2023). "In addition, Noggin has been found to be able to inhibit angiogenesis in lung cancer models, suggesting that its loss or downregulation in lung cancer cells may contribute to angiogenic switch that occurs in tumor progression." (PMID 38012621, 2023). "Here, we found that Noggin downregulation also facilitated brain metastatic colonization of lung cancer cells." (PMID 38012621, 2023). "All these studies suggest that Noggin plays an important role in regulating lung cancer progression and metastasis." (PMID 38012621, 2023). "Noggin expression is downregulated in various types of cancer, including stomach, prostate, and lung cancers." (PMID 38012621, 2023). "In lung cancer cells, Noggin abrogated angiogenic activity enhanced by BMP-2." (PMID 38012621, 2023). "Thus, Noggin might provide a potential therapeutic target for inhibiting brain metastasis progression in a subset of patients with lung cancer." (PMID 38012621, 2023). "Our results suggest that lung cancer cells undergo MET and lose their motility and invasiveness during brain metastatic colonization, which is dependent on Noggin." (PMID 38012621, 2023). "Our findings demonstrate that during brain metastatic colonization, lung cancer cells undergo MET and exhibit decreased motility and invasiveness, which is dependent on Noggin." (PMID 38012621, 2023). "In cases of lung cancer with brain metastasis that do not have targetable genetic alterations, Noggin could be an alternative target for preventing the progression of brain metastasis." (PMID 38012621, 2023).
lung fibrosis (2 papers, 2015 to 2021). "Here we show that changes in endogenous BMP signaling in noggin haploinsufficient mice reduce lung fibrosis in the bleomycin-induced model, suggesting that BMPs are homeostatic signals in the lung." (PMID 25849157, 2015). "In fact, a previous experimental study using noggin-insufficient mice revealed that the upregulation of BMP signaling could reduce the severity of bleomycin-induced lung fibrosis." (PMID 33770226, 2021).
neuroblastoma (2 papers, 2015 to 2025). Neuroblastoma (NB) is the most common solid, extracranial childhood tumor. "The activities we observed in neuroblastoma cells upon exposure to BMP are especially consistent with BMP’s function as a negative regulator of neural commitment of human embryonic stem cells, where treatment with BMP inhibitors such as noggin causes neuronal differentiation." (PMID 40021625, 2025). "It has been recently shown that specific members of the differential screening selected gene aberrative in neuroblastoma (DAN) family and BMP antagonists such as Noggin might be responsible for delaying and inhibiting spinal fusion, although such cytokines are applied at very high doses." (PMID 26809343, 2015).
osteoporosis (2 papers, 2022). A condition of reduced bone mass, with decreased cortical thickness and a decrease in the number and size of the trabeculae of cancellous bone (but normal chemical composition), resulting in increased fracture incidence. "Noggin also inhibits OB differentiation, and its overexpression in mice resulted in significantly reduced bone formation and osteoporosis." (PMID 35880162, 2022).
pancreatic cancer (2 papers, 2024 to 2025). "In contrast, the growth of SMAD4-mutant pancreatic cancer PDOs was unaffected by Noggin/A83-01 withdrawal." (PMID 39195202, 2024). "Pancreatic cancer PDOs with wildtype SMAD4 were undetectable using IHC, because of the existence of the BMP/TGF-β-inhibiting molecules, Noggin and A83-01, in the organoid culture medium." (PMID 39195202, 2024).
skin tumor (2 papers, 2011 to 2020). "We previously reported that Myo/Nog cells expressing G8, Noggin and MyoD mRNA were associated with the hair follicles, rapidly responded to epidermal abrasion and home to skin tumors." (PMID 32833999, 2020). "Double transgenic mice expressing BMP as well as noggin under control of the Nse promoter were used to rescue the skin tumor phenotypes." (PMID 22168923, 2011).
anemia (1 paper, 2021). A reduction in the number of red blood cells, the amount of hemoglobin, and/or the volume of packed red blood cells. "Furthermore, treatment with LDN-193189, noggin and ALK3-Fc (BMP antagonists) can inhibit IL-6-induced hepcidin expression, leading to improved turpentine-induced anemia." (PMID 34679725, 2021).
bladder cancer (1 paper, 2022). "The effect of some of the currently used factors, such as the Wnt/β-catenin and MAPK modulators, noggin, and hepatocyte growth factor, remains to be established in bladder cancer." (PMID 35565191, 2022).
brachydactyly (1 paper, 2015). A disease characterized by the presence of brachydactyly, including syndromic and non-syndromic forms. "Its phenotype is very similar to that caused by mutations in Noggin, a modulator protein counteracting GDF-5 activity, and rather different to other mutations in GDF-5 found in patients with brachydactyly and Du Pan syndrome (also known as fibula aplasia complex brachydactyly)." (PMID 26385096, 2015).
cerebral infarct (1 paper, 2012). "NOG gene (Noggin), was downregulated in the PI area at 3 d and HES5, involved in neurogenesis, was downregulated in both the core and PI areas at 24 h but only in the core of the lesion at 3 d after cerebral infarct." (PMID 23284893, 2012).
chondrosarcoma (1 paper, 2017). A malignant cartilaginous matrix-producing mesenchymal neoplasm arising from the bone and soft tissue. "To test the Noggin-Ror2 synergy in a model system that is more relevant to skeletal development we decided to use the rat chondrosarcoma (RCS) cell line." (PMID 28523267, 2017). "Rat chondrosarcoma chondrocytes (RCS), however, are not able to respond to Noggin in this fashion unless growth arrest is induced by FGF2." (PMID 28523267, 2017).
colon adenocarcinoma (1 paper, 2022). "We took ID1 expression as an indicator for active BMP signalling and noggin for inhibited signalling and analysed patient data from the Cancer Genome Atlas (TCGA; cohorts colon adenocarcinoma (COAD) plus rectum adenocarcinoma (READ))." (PMID 34841646, 2022).
conductive hearing loss (1 paper, 2017). "Interestingly, a mutation within the heparin binding site of Noggin which reduces its affinity underlies the congenital disorders of proximal subphalagism and conductive hearing loss, strongly implicating heparin-binding in the functioning of Noggin during development." (PMID 28468283, 2017).
cyst (1 paper, 2017). A sac-like closed membranous structure that may be empty or contain fluid or amorphous material. "The aberrant surface phenotype of the thymic epithelium is magnified in Foxn1+/−;Foxn1:Noggin mice, in which the thymus consists of a large cyst; keratin 5-positive epithelial cells occupy a basal location and only few, if any, haematopoietic cells are present." (PMID 28819138, 2017).
demyelination (1 paper, 2013). "We have previously shown that BMP4 infusion increases numbers of OPCs during cuprizone-induced demyelination, while infusion of Noggin, an endogenenous antagonist of BMP4 increases numbers of mature oligodendrocytes and remyelinated axons following recovery." (PMID 23650566, 2013).
depression (1 paper, 2018). "Inhibiting hippocampal neurogenesis using BMP and Noggin transgenic mice which regulate BMP signaling resulted in blockage of chronic pain but did not affect pain-induced depression." (PMID 30197587, 2018).
disc degeneration (1 paper, 2008). "Clinically, noggin may be a potential target for disc degeneration as it is a well-known inhibitor of the anabolic TGFβ/bone morphogenetic protein signaling pathway and is upregulated by FGF2 in bovine disc tissue." (PMID 18435858, 2008).
embryonal rhabdomyosarcoma (1 paper, 2020). A poorly circumscribed morphologic variant of rhabdomyosarcoma. "In this study, the myogenic determination factor 1 (MYOD1) and the morphogenetic protein Noggin (NOG) were investigated in an embryonal rhabdomyosarcoma (ERMS) and a rhabdoid tumor (RT) cell line." (PMID 32300280, 2020).
enthesitis (1 paper, 2016). Inflammation at the site of insertion of ligaments, tendons, and other fibrous structures into bone. "Thus, inhibition of BMP signaling by overexpression of noggin, which is an endogenous BMP antagonist, inhibited the onset and the progression of enthesitis." (PMID 26801240, 2016).
esophagitis (1 paper, 2022). An acute or chronic inflammatory disease affecting the esophageal wall. "In this study, we demonstrated that inhibition of BMPs by Noggin reduced development of EAC in a surgical esophagitis-IM-EAC rat model." (PMID 34718471, 2022).
Ewing sarcoma (1 paper, 2020). A small round cell tumor that lacks morphologic, immunohistochemical, and electron microscopic evidence of neuroectodermal differentiation. "Treatment of Ewing sarcoma cells with noggin eliminated phosphorylated Smad1/5." (PMID 33147457, 2020). "This indicates that noggin efficiently blocked BMP signaling in Ewing sarcoma cells." (PMID 33147457, 2020).
Glucose intolerance (1 paper, 2022). Glucose intolerance (GI) can be defined as dysglycemia that comprises both prediabetes and diabetes. "Adipose specific knockout of noggin enhances BMP activity, causing significant increase in white adipose tissue, fatty liver, and glucose intolerance in mice fed a high-fat diet." (PMID 35641992, 2022).
hematoma (1 paper, 2022). A hematoma is a collection of blood from a vascular structure into an extravascular space. "In line with this, the expression of osteogenic differentiation markers RUNX2, ALP, BMP4, and Noggin as well as the chondrogenic differentiation marker SOX9 were all significantly lower in smokers’ hematomas (comp." (PMID 35621464, 2022).
Hip dysplasia (1 paper, 2019). The presence of developmental dysplasia of the hip. "Future research should focus on how these regulatory variants affect the expression of noggin in canine hips, and what the roles of noggin and the other revealed loci are in canine hip dysplasia." (PMID 31323019, 2019). "Besides a larger replication study and investigation of the other candidate genes on chromosomes 1 and 9, future research should focus on what kind of biological effects the variants have on the expression of noggin in the canine hips and on the development of hip dysplasia." (PMID 31323019, 2019). "It is possible that the regulation of noggin expression levels is suboptimal in hip joints of German Shepherds prone to develop moderate-to-severe hip dysplasia." (PMID 31323019, 2019).
hypophosphatasia (1 paper, 2021). Hypophosphatasia (HPP) is a rare heritable metabolic disorder characterized by defective mineralization of bone and/or teeth in the presence of reduced activity of unfractionated serum alkaline phosphatase (ALP). "It is worth noticing that the orientation of hypophosphatasias was intraversive in the WT soft palates, but extraversive in the Osr2-creKI;pMes-Noggin soft palates." (PMID 34557486, 2021).
leiomyosarcoma (1 paper, 2019). An uncommon, aggressive malignant smooth muscle neoplasm, usually occurring in post-menopausal women. "Thirty nine percent of subjects with leiomyosarcoma and approximately one third of the sections from these tumors of smooth muscle origin contained small numbers of G8+/noggin+ cells." (PMID 30973903, 2019).